ENSG00000272772 (novel protein)
Gene: Protein-coding gene on chromosome 5 (134,157,088 to 134,225,861, reverse strand). Ensembl gene ENSG00000272772.
Genetic constraint (gnomAD): Loss-of-function variants: 2 observed, 5.35 expected, observed/expected ratio (o/e) 0.37, 90% interval 0.15 to 1.17. That is too few expected variants to judge how well the gene tolerates losing a copy. Missense variants: 25 observed, 38.22 expected, observed/expected ratio (o/e) 0.65, 90% interval 0.48 to 0.91. Synonymous variants: 25 observed, 15 expected, observed/expected ratio (o/e) 1.67, 90% interval 1.18 to 1.95.